HLA-C (major histocompatibility complex, class I, C)
Diseases named in the same sentence as HLA-C in open-access papers (continued):
Sharing a sentence is not in itself a finding about the gene and the disease.
morphea (1 paper, 2024). "Moreover, the HLA-class II—HLA-DQB1*02:01, HLA-DRB1*03:01 and HLA-DQA1*03:00, and HLA-class I—HLA-C*08 and HLA-C*15—have also been implicated in morphea patients." (PMID 39685593, 2024).
oral lichen planus (1 paper, 2022). Oral lichen planus is a chronic inflammatory oral condition of unknown aetiology characterized by T-cell-mediated chronic immune response and abnormal epithelial keratinization cycle. "A recent study identified abnormal expression of 135 circRNAs in oral lichen planus (OLP); among them, chr6:31238920–31324013‐, whose host gene is HLA‐C (a regulator of the human immune system), is significantly highly expressed in OLP." (PMID 35770323, 2022).
Oral ulcer (1 paper, 2022). Erosion of the mucous mebrane of the mouth with local excavation of the surface, resulting from the sloughing of inflammatory necrotic tissue. "Among them, the expression of inflammation-related genes such as CCRL2, HLA-C, GSDMB, HLA-DPB1, and MAPT increased in patients with oral ulcers." (PMID 35958581, 2022).
palmoplantar pustulosis (1 paper, 2024). A rare skin disease characterized by chronic eruption of sterile pustules on an erythematous and desquamative background, affecting the palms and soles, sometimes also the lateral aspects of hands and feet. "A study done in a Han Chinese population showed that palmoplantar pustulosis was observed in HLA-C*06:02-negative patients." (PMID 39261909, 2024).
papillary thyroid carcinoma (1 paper, 2023). "For example, the HLA-C*04 and HLA-C*15 alleles have been linked to a greater tendency to develop papillary thyroid carcinoma." (PMID 37465164, 2023).
pleural cancer (1 paper, 2025). A primary or metastatic malignant neoplasm affecting the pleura. "Analysis of 11 antigens that regulated NK cell activity in pleural cancer revealed that HLA-E and HLA-C were the predominant tumor-associated antigens." (PMID 40959273, 2025).
prediabetes (1 paper, 2025). "A total of 130 DMCs across 99 genes, including LCLAT1, HLA-C, ZNF714, and HOOK2, were shared by prediabetes and T2D groups." (PMID 41373473, 2025). "Compared to the control group, we detected 130 DMCs that were shared between the prediabetes and T2D groups, with LCLAT1, HLA-C, NINJ2, ZNF714, CNDP2, and HOOK2 among the top differentially methylated genes." (PMID 41373473, 2025).
rash (1 paper, 2009). "The aim of the present study was to evaluate the effects of different HLA-C alleles on rash associated with nevirapine in patients who started highly active anti-retroviral therapy (HAART) containing nevirapine in Thailand." (PMID 19845952, 2009). "In the study reported here, we genotyped HLA-C alleles of 39 patients with NVP-induced rash and 60 NVP-tolerant Thai patients, and found that frequency of HLA-Cw*04 was higher in NVP-induced rash Thai patients than in NVP-tolerant patients." (PMID 19845952, 2009). "To know whether or not higher levels of HLA-C gene expression associated with NVP-induced rash, we genotyped rs9264942 SNP by TaqMan SNP genotyping system." (PMID 19845952, 2009).
retinal detachment (1 paper, 2011). An eye emergency condition which may lead to blindness if left untreated. "Within the genes identified, the expression of the major histocompatibility complex I gene HLA-C enables diagnosis of the disease, while PKD2L1 and SLCO4A1 -which are both down-regulated- act synergistically to provide an estimate of the duration of the retinal detachment process." (PMID 22174898, 2011).
sarcopenia (1 paper, 2020). Progressive decline in muscle mass due to aging which results in decreased functional capacity of muscles. "The lean muscle mass-only phenotype maintained the significance of the previously observed HLA types, except in the case of HLA-C*01:02 in the female-only cohort which lost its significant association with sarcopenia." (PMID 30772894, 2020).
skin tumors (1 paper, 2014). "This suggests a deregulation of HLA-C mediated immunity in individuals with SCC, that potentially relates to the development of skin tumors." (PMID 25083782, 2014).
smallpox (1 paper, 2022). A condition that is caused by infection with Variola, and that is characterized by small, raised bumps. "Importantly, KIRs and HLA polymorphisms are linked to infectious disease outcome and if the selective modulation of HLA-C is conserved in other orthopoxviruses, such as variola virus, this might have contributed to pathogenesis of smallpox." (PMID 35727847, 2022).
Splenomegaly (1 paper, 2025). Abnormal increased size of the spleen. "Age, gender, disease distribution, fever occurrence, white blood cell count (WBC), splenomegaly, and the administration of antibiotics were similar between patients positive and negative for anti-HLA-C autoantibodies." (PMID 39731480, 2025). "The findings demonstrated that only anti-HLA-C autoantibody positive could nearly predict the occurrence of PTR (OR = 9.205, 95%CI: 0.896–94.586, p = .062), while splenomegaly and anti-HLA-C autoantibody positive were both the independent risk factor for P/P PTR." (PMID 39731480, 2025).
thalassemia (1 paper, 2017). An inherited blood disorder characterized by a decreased synthesis of one of the polypeptide chains that form hemoglobin. "La Nasa and colleagues studied KIR and HLA-C genotype in a homogeneous group of 45 thalassemia patients undergoing bone marrow transplantation." (PMID 28627158, 2017).
trachoma (1 paper, 2014). "The data presented indicate that HLA-C genotypes are important determinants of conjunctival scarring in trachoma and that KIR2DL2/KIR2DL3 heterozygosity further increases risk of conjunctival scarring in individuals carrying HLA-C2." (PMID 24651768, 2014).
VKH disease (1 paper, 2011). "The differences in the frequencies of HLA-C and KIR-HLA-C complex between patients with VKH disease and the control group were statistically significant." (PMID 22219647, 2011). "Comparison of HLA-class I (-Cw) and KIR - HLA-C complex in a cohort of Saudi patients with VKH disease and control subjects." (PMID 22219647, 2011).
tumor (1,764 papers, 1984 to 2026). "We moved forward with the allele HLA-C*07:02 because of its strong affinity and predicted a preference for binding to tumor-derived peptides." (PMID 41246330, 2025). "A copy-neutral LOH on chromosome 6 encoding the HLA-C*08:02 class I major histocompatibility complex molecule was found to facilitate tumor evasion from T-cell transfer therapy." (PMID 41184283, 2025). "Specifically, we found upregulation of genes associated with antigen presentation (HLA-A, HLA-B, and HLA-C) following tumor treatment with radiotherapy." (PMID 40858520, 2025). "HLA‐C, a key immune system component, can undergo mutations or loss of heterozygosity, impairing immune surveillance and contributing to tumour escape." (PMID 41017066, 2025). "The first positive cluster reflected associations of MHC class I neoantigens (specifically those with predicted binding affinity to HLA-A and HLA-C) with tumor-associated macrophages, regulatory T cells and γδ T cells." (PMID 36585450, 2023). "We found that gap junction signaling pathways (ADCY8 and PPP1R9A) were upregulated and cell adhesion signaling pathways (VSIR and HLA-C) were downregulated, which is associated with tumor growth metastasis." (PMID 37511481, 2023). "The disappearance of the chromosome 6 haplotype encoding the HLA‐C*08: 02 molecules in tumor cells leads to the downregulation of MHCs, resulting in an escape from NRTs recognition." (PMID 37970536, 2023). "In clinical cases, it has been reported that the loss of expression of an allotype very similar to HLA-C*08:02 generates an immune evasion in tumour tissue." (PMID 37465164, 2023). "With all six samples taken together, we found that peptides predicted to bind to lost alleles had increased peptide intensity in tumor samples compared to normal samples for HLA-A, HLA-B and HLA-C alleles." (PMID 35414054, 2022). "Of note, many of the phosphopeptides identified were attributed to HLA-C*07, a common allele (37-69%) across European and African populations and known to contribute significantly to tumor immunity." (PMID 34504498, 2021). "A recent report elucidated loss of heterozygosity (LOH) at the HLA alleles; in particular, loss of HLA-C*08:02 was observed in a resistant lesion treated with tumor-infiltrating lymphocytes composed of cytotoxic T cell clones targeting the KRAS G12D mutation." (PMID 31963413, 2020). "In this respect, C1/C2 individuals are in a privileged position, because even when a tumor cell retains one HLA-C allele, it is still vulnerable to lysis by these NK cells which express KIR recognizing a product of the second allele which had been lost." (PMID 23372569, 2013). "All patients with certain major histocompatibility complex (MHC) class I alleles had a detectable antitumor T cell response (e.g., HLA-C∗07:01), suggesting that some of the tumor-reactive CD8 T cells might be restricted to these alleles." (PMID 40730190, 2025). "The loss of the HLA-C*08:02 molecule provides an immune escape mechanism for the tumor." (PMID 38384647, 2024). "Analysis of a tumor sample upon progression at 9 months revealed loss of HLA-C*08:02 expression." (PMID 39796666, 2024). "While classical HLAs, predominantly encoded by HLA-A, HLA-B, and HLA-C genes, have enjoyed extensive scrutiny for their involvement in tumor immunosurveillance, in anti-tumor immunity, and in immune escape mechanisms, the less understood area of non-classical HLAs has also garnered attention." (PMID 39766165, 2024). "In the case of genital herpes type II, it has been identified that the C*04 and C*02 alleles of HLA-C are present in individuals with greater susceptibility to infection and severe development of the pathology that could trigger neoplasms." (PMID 37465164, 2023).
tumor (continued). "Of note, mutations within the HLA class I alleles, mostly in HLA-A and HLA-C, were identified in the tumour lesion obtained from patient PanTT39, which may have given rise to preferential expansion of CD4+ T cells recognising the nominal tumour target antigen bound to HLA class II molecules." (PMID 30377343, 2019). "Notably, the treatment with CD8+ cells targeting mutant KRAS has been successful against a cancer that expressed both the specific G12D mutation and the HLA-C*08:02 restriction molecule, thus providing key evidence of the importance of HLA molecule downregulation for tumour immune evasion." (PMID 28404796, 2017). "For example, the circTBC1D15-derived neoantigen has been proved to be presented by HLA-A, HLA-B, and HLA-C, drastically reducing the survival rate of the tumor organoid." (PMID 39832278, 2025). "Defects in the TAP1 gene, a component of the antigen processing machinery, and the HLA Class I genes (HLA-A, HLA-B, and HLA-C) enable tumor cells to evade immune destruction by CD8+ T cells due to impaired presentation of tumor antigens." (PMID 41295262, 2025). "We considered two types of target cells - healthy and diseased (virally infected or tumor) expressing normal and lower copy numbers (or abundances) of HLA-C molecules, respectively." (PMID 40196617, 2025). "Correlation analysis indicated positive associations of CD160 ligands such as TNFRSF14 and HLA-C, and NKG2D (KLRK1) ligands MICA and MICB with the tumour-infiltrating CD56bright NK and CD8+ TEM cells." (PMID 39877370, 2024). "Among these genes, several immune system genes, such as COL18A1, S100A2, ITGA4, HLA‐C, and ADCYAP1, have previously been linked to tumor progression in PCa." (PMID 39162297, 2024). "Classical type I HLA molecules (HLA-A, HLA-B, and HLA-C) play a critical role in the immune response against tumor cells by presenting tumor-specific antigens on the surface of cells for recognition by cytotoxic T cells." (PMID 38383447, 2024). "This alternative approach to scRNA-seq using the C1 Fluidigm platform also highlighted a statistically significant increase in the expression of three classical MHC-I genes—HLA-A, HLA-B, and HLA-C—in tumor T cells from plaque/tumor late-stage skin lesions." (PMID 38272918, 2024). "We also observed that many of the high-DAI neo-epitopes on all tumor types were constituted preferentially with HLA-A and HLA-B over HLA-C." (PMID 37427594, 2023). "In terms of HLA expression, HLA-A, HLA-B, HLA-C, HLA-E, HLA-F, HLA-G, and HLA-J were significantly more highly expressed in C2 than in C1, indicating that tumour subtypes differ in the activation of immune cells." (PMID 37691922, 2023). "The expression of class I HLA molecules, which are responsible for antigen presentation to tumor-killing T-cells, including HLA-A, HLA-B, HLA-C, HLA-E, HLA-F, and B2M, was downregulated in 7, 8, 5, 10, 5, and 14 patients, respectively." (PMID 37152992, 2023). "The cumulative HLA allele frequency coverage per tumor type or subtype in the corresponding PDX models ranged from 0.40 to 0.96 for HLA-A, from 0.27 to 0.80 for HLA-B, and from 0.23 to 0.97 for HLA-C." (PMID 37723198, 2023). "Only one tumor sample of CCRCC lost one allele inall HLA-A, HLA-B,and HLA-C genes, and two tumor samples of LUAD lost one allele inHLA-A and HLA-C genes." (PMID 37857377, 2023). "Search settings were as follows: Dataset: Adult and CCGA, Tumor type: Primary, Gene: HLA-A, HLA-B, and HLA-C, Histology: GBM, Subtype: All, Gender: All, IDH status: Wild-type, Cutoff: Median." (PMID 37382632, 2023).
tumor (continued). "An effective anti-tumor immune response requires antigen presentation, in which MHC class 1 molecules, such as HLA-A, HLA-B, and HLA-C, present antigenic peptides from tumor cells or DC to CD8 T cells." (PMID 37884639, 2023). "Using HLA-C*08:02 dsSCD we detected two T cell populations recognizing tumor-derived peptides, one directed against a tumor neoepitope and the other specific for a novel NY-ESO-1 epitope." (PMID 38239352, 2023). "By contrast, only three tumors (one individual) demonstrated methylation at HLA-B, and only one tumor had HLA-C or B2M methylated." (PMID 36585450, 2023). "HLA-C molecules on the surface of tumor cells interact with inhibitory receptor KIR2DL on the surface of NK cells, inhibiting the cytotoxicity of NK cells, resulting in immune escape of tumors." (PMID 36507493, 2022). "Together this demonstrates the therapeutic efficacy of alloreactive ADAPT-NK against HLA-C mismatched tumor cells and underscores their ability to deliver a maximized missing-self response in settings with high levels of mismatched HLA-C." (PMID 36319065, 2022). "Tumor cells bind to the NK cell surface receptor KIR2DL via HLA-C molecules, and activate phosphorylation of tyrosine residues in the cytoplasmic ITIM sequence, leading to the recruitment of protein tyrosine phosphatases (PTPs) SHP-1 and SHP-2." (PMID 36507493, 2022). "A significant reduction in tumor burden underlined the importance of TCR profile and the binding kinetics between HLA-C and TCR interaction in the specific, persistent, efficient TCR therapy." (PMID 35014625, 2022). "Significant negative correlations were found in 10/10 HLA-A probes, 5/13 HLA-B probes, and 10/11 HLA-C probes in the tumor samples, and only 1/10, 3/13, and 2/11 for HLA-A, HLA-B, and HLA-C normal samples, respectively." (PMID 36050516, 2022). "The responsiveness of blood- and tumor-derived NK-cells was significantly reduced after stimulation with HLA-C expressing K562 cells when compared to HLA class-I deficient K562 cells." (PMID 35474089, 2022). "KIR2DL is an inhibitory receptor, and tumor cells expressing HLA-C interact with KIR2DL and thus the activity of NK cells can be inhibited." (PMID 36507493, 2022). "In summary, tumor cells interact with inhibitory receptors on the surface of NK cells through HLA-C molecules, which negatively regulate the cytotoxicity of NK cells." (PMID 36507493, 2022). "HLA-C, which belongs to HLA-I and can present endogenous tumor antigens to kill tumor cells effectively, was less expressed in the high-risk group, while HLA-II, such as HLA-DPB2, HLA-DQB2, HLA-DOA, and HLA-DQA2, showed an increase in the high-risk group." (PMID 35754846, 2022). "HLA-C can be distributed in normal cells, stimulated cells and tumor cells, and is the presenting molecule of endogenous antigens." (PMID 36507493, 2022). "ADAPT-NK cells showed high degranulation capacity and efficient killing of HLA-C/KIR mismatched tumor cell lines as well as primary leukemic blasts from AML patients." (PMID 36319065, 2022). "Tumor cells can also inhibit NK cell cytotoxicity through the binding of HLA-C molecules to inhibitory receptors, resulting in immune escape." (PMID 36507493, 2022). "There was a 2.8-fold increased percentage for HLA-A*25 (normal 8/172, tumor 11/84, p = 0.02) and a 2.1-fold increase in HLA-C*06 (normal 21/172, tumor 21/84, p = 0.01) in HNSCC patients." (PMID 35954492, 2022). "A group of tumor lines displayed negligible expression of HLA-C and were subsequently killed equally well by HLA-C/KIR-matched and mismatched ADAPT-NK cells (online supplemental sFigure 3C–F)." (PMID 36319065, 2022). "NK–tumor interactions included HLA-C/KIR2DL4, HLA-E/CD94 (KLD1), TIM3 (HAVCR2)/Galectin-9, CD96-PVR/Nectin1 and TIGIT-PVR/Nectin2." (PMID 33671917, 2021).